CD28 (CD28 molecule)
Diseases named in the same sentence as CD28 in open-access papers (continued):
Sharing a sentence is not in itself a finding about the gene and the disease.
glioma (30 papers, 2012 to 2025). A benign or malignant brain and spinal cord tumor that arises from glial cells (astrocytes, oligodendrocytes, ependymal cells). "Although current studies have demonstrated that tumor infiltration of CD28+ CD8+ T cells is associated with better prognosis in glioma 54, CD45RA, as a marker of naive T cells, indicates that CD28+ CD45RA+ CD8+ T cells possess characteristics of naive T cells." (PMID 40657381, 2025). "The results indicated that CD28+CD45RA− CD8dim AC mediated the risk of Bacteroides A plebeius A on glioma in both all_glioma and non_GBM, with mediation effect proportions of 2.99% and 3.66%, respectively." (PMID 41384027, 2025). "Of note, gene set enrichment analysis revealed that genes associated with PD-1 and CD28 signaling were increased in high-grade tumors relative to low-grade gliomas." (PMID 36644324, 2022). "Our mediation analysis revealed that the risk effect of Bacteroides A plebeius A on glioma was mediated by CD28+CD45RA−CD8dim Treg cells, suggesting a pathway where microbiota influences T‐cell regulation, potentially fostering a permissive tumor microenvironment." (PMID 41384027, 2025). "In terms of T cells, we discovered that the absolute count of CD28+CD45RA+CD8+ T cells and SSC-A on CD8+ T cells were also associated with an increased risk of glioma." (PMID 40657381, 2025). "This dysfunction, exacerbated by the glioma TME, underscores the potential of targeting the CD28 pathway to augment glioma immunogenicity." (PMID 38342925, 2024). "A third-generation EGFRvIII CAR-T cell with a CD28 and a 4-1BB co-stimulatory domain was evaluated in a syngeneic, fully immune-competent mouse model after challenge with the murine glioma parental cell lines SMA560vII." (PMID 37443804, 2023). "Comparison was made to T cells stimulated by anti-CD3/anti-CD28 antibodies in the presence of either autologous monocytes or autologous MDSC-enriched monocytes (“MDSCs”) generated by culture with glioma-conditioned media." (PMID 28666020, 2017). "The association between CD28+ CD45RA+ CD8+ T cells and increased glioma risk may be mediated through the exhaustion of naive T cells." (PMID 40657381, 2025). "CD28+CD45RA+CD8+ T cells and SSC-A on CD8+ T cells may increase the risk of glioma through lower anti-tumor immunity." (PMID 40657381, 2025). "Both results demonstrated that gliomas impact the proportion of CD28− CD8+ T cells (p of GICC study = 0.0329, p of UCSF/Mayo study = 0.0449)." (PMID 41155216, 2025). "To investigate whether the metabolic regulators prevent decreases in OXPHOS, we chronically stimulated CAR-T cells with SB28 mEGFRvIII gliomas or anti-CD3/anti-CD28 beads under hypoxia." (PMID 38386420, 2024). "CD28 expression is altered following DGH or TMZ treatment in glioma." (PMID 35625673, 2022). "The unique epigenetic, transcriptional, and post-translational changes in T cells triggered by CD28 ligation cannot be achieved by TCR ligation alone, making it a significant target for therapeutic modulation in glioma treatment." (PMID 38342925, 2024). "To first evaluate the effect of activation domains on anti-glioma activity of mB7-H3 CAR T-cells, we cloned a CD28-CAR with intact CD3ζ (28.ζ)." (PMID 37333156, 2023). "We detected the surface expression of CD28, CD45RA, CD45RO, CCR7, and CD44 in CTL and found CD28, CD45RO, and CD44 were expressed in glioma CD133+ CSC-reactive CTL, whereas CD45RA and CCR7 were rarely expressed." (PMID 28881826, 2017). "Also, CAR-T cells directed to PDPN by a construct composed of NZ-1-based single-chain variable fragments and CD28, 4-1BB and CD3 ζ intracellular domains have shown good efficiency against glioma cells both in vitro and in vivo glioma xenografts." (PMID 40677711, 2025). "Through analysis of glioma samples in the CGGA and TCGA databases, we found that CDCA7 expression level was significantly correlated with tumor-related immunosuppressive molecules, including CD80, CD276, CD28, PDCD1LG2, and TNFSF4." (PMID 37510310, 2023).
glioma (continued). "By contrast, nonspecific activation with anti-CD3/anti-CD28 induced proliferation in glioma and BrM TILs to a similar extent, suggesting that functional T cells can be found in both pathologies." (PMID 37217652, 2023). "However, it has been reported that glioma cell lines-derived exosomes lack antigen-presentation and the surface co-modulatory machinery CD80 and CD86 able to cross-react with CD28." (PMID 28107450, 2017). "In addition, we found that cell-to-cell contacting with patient-derived CD57+ glioma cells induced rapid upregulation of CD57 on activated CD8+ T cells, independent of antigen recognition and without concomitant loss of CD28 or CD27." (PMID 25426558, 2015).
asthma (25 papers, 2009 to 2025). "In our study, we observed significant mediation effects where 1‐myristoyl‐2‐arachidonoyl‐GPC (14:0/20:4) levels mediated a substantial proportion of the effect of CD3 on CD28+ CD4+ T cells on asthma risk." (PMID 40551049, 2025). "We found that ICTs (CD24 on IgD+ CD38br and CD3 on CD28+ CD4+) influence asthma through two pathways, mediated by PMs (S‐methylcysteine sulfoxide levels and 1‐myristoyl‐2‐arachidonoyl‐GPC (14:0/20:4) levels)." (PMID 40551049, 2025). "Due to the central role of type 2 inflammation, CD28 is also considered as the therapeutic target of asthma." (PMID 39342146, 2024). "Here, for the first time, we have shown that PBMCs from patients with asthma demonstrate a time-of-day difference in their response to LPS with CD3/CD28 stimulation, as well as to dexamethasone suppression." (PMID 37404842, 2023). "Co-stimulation via CD28 is the most important pathway for the initial activation of naïve T-cells, a key cell type in asthma." (PMID 37404842, 2023). "Stimulating PBMCs with a combination of low-dose LPS and Human T-Activator CD3/CD28 allows us to replicate some of the complex immune pathways at play in asthma." (PMID 37404842, 2023). "More importantly, we found that TNFα/anti-CD3/CD28-induced IL-8 production was dexamethasone-insensitive particularly in severe asthma." (PMID 22911818, 2012). "Therefore, CD28 is considered as a therapeutic target of asthma, blocking CD28-mediated costimulation is highly effective in preventing OVA-induced airway inflammation." (PMID 39342146, 2024). "c-CBL/LCK/c-JUN/ETS1/CD28 axis was partially involved in childhood asthma, and may provide novel insights for clinical treatment for asthma." (PMID 39342146, 2024). "c-CBL/LCK/c-JUN/ETS1/CD28 axis was beneficial for asthma, and may provide novel targets for asthma therapy." (PMID 39342146, 2024). "For example, among the strongest associations with the lead SNPs at the following loci include: CLEC16A, CD28, MICA, and ELMO1 with eosinophil counts; AHI1 with monocyte and neutrophil counts, asthma, and hay fever (also shared by CD28); and MICA with type 1 diabetes." (PMID 37120605, 2023). "The activated T cells in the airway wall are associated with inflammation of asthma, and the subsets of T cell antigens have attracted extensive attention by researchers, such as the T cells of CD4+(T helper), CD8+, CD25+, CD28, CD29, CD39+, and CD73." (PMID 30210753, 2018). "We found that genes involved in ribosome, cytokine-cytokine receptor interaction, antigen receptor signaling pathway, hematopoietic cell lineage and asthma were significantly enriched among genes affected by Akt inhibition in the presence of CD3/CD28 stimulation." (PMID 24627779, 2013). "In contrast, the overall results for CD28 are more consistent with the previous studies showing the lack of association with asthma." (PMID 19852851, 2009). "c-CBL alleviated asthma and suppressed Th2 differentiation by facilitating LCK ubiquitination, interrupting c-JUN activation and CD28 expression in vivo and in vitro." (PMID 39342146, 2024). "Among 14 analytes measured in conditioned media from individuals with asthma, nine significantly increased after stimulation with LPS and CD3/CD28 activation compared to untreated controls, and of these, four were suppressed with dexamethasone treatment." (PMID 37404842, 2023). "The results of our ex vivo study strongly suggest a contrasted picture of T cell activation in allergic rhinitis and asthma, with distinct patterns of Th1, Th2 and Treg profiles and expression of ICOS, CD28 and CTLA-4 co-receptors." (PMID 21356099, 2011). "It suggested that c-JUN and ETS1 may be involved in regulation of asthma development and Th2 differentiation by controlling CD28 expression, and LCK may function by control c-JUN/ETS1/CD28 axis." (PMID 39342146, 2024).
asthma (continued). "Only PBMCs from individuals with asthma showed significant responses to LPS/CD3/CD28 stimulation; no significant changes were observed in PBMCs from healthy individuals." (PMID 37404842, 2023). "A low-concentration LPS stimulation (10 ng·mL−1) in combination with CD3/CD28 activation was used in PBMC experiments, since LPS is ubiquitous in the environment and may influence the development of asthma." (PMID 37404842, 2023). "The expression levels of CD28, CD59, LAG3, TCRab and TIGIT were higher, while CD45, CD45RO, RORγ, OX40 and Tbet lower in cluster 16 in acute pneumonia, stable pneumonia, acute asthma and stable asthma." (PMID 34841705, 2021). "MSCs appeared to suppress the activation of T helper cells in PBMCs cultured in vitro after stimulation with antihuman CD3 and CD28 antibodies in the children with asthma but not in the children without asthma." (PMID 31673233, 2019). "Our objective was to assess whether allergen-induced T cell activation differs from allergic rhinitis to allergic rhinitis with asthma, and explore the role of ICOS, CD28 and CTLA-4." (PMID 21356099, 2011). "CD3+CD28-stimulated accumulation of IL-13+ T cells was also greater in female subjects, but was not influenced by asthma status." (PMID 20667106, 2010). "MSCs could suppress the proliferation of CD4+ T cells in PBMCs cultured in vitro after stimulation with antihuman CD3 and CD28 antibodies in both children with and without asthma." (PMID 31673233, 2019). "MSCs could suppress the proliferation of CD8+ T cells in PBMCs cultured in vitro after stimulation with antihuman CD3 and CD28 antibodies in both the children with and without asthma." (PMID 31673233, 2019). "Interestingly, increased accumulation of IL-13+ T cells under CD3+CD28-stimulatory conditions was also observed in females, but was in this case independent of asthma status." (PMID 20667106, 2010). "It is to note that the role of CD4+CD25+ T cells could not be tested in the allergic asthma model since CD28−/− mice do not develop OVA-induced asthma." (PMID 20628601, 2010). "For CD3+CD28-stimulated accumulation of IL-13+ T cells, there was a significant difference between male and female subjects overall (p = 0.0001) and within asthmatic (p < 0.01) and control (p < 0.03) populations, but not between asthma and control populations within the same gender." (PMID 20667106, 2010).
atherosclerosis (25 papers, 2012 to 2025). A disease characterized by the build-up of fatty material and calcium deposition in the arterial wall resulting in partial or complete occlusion of the arterial lumen. "CMV exposure has been correlated with increased incidence of both cancer and atherosclerosis after kidney transplant concurrent with accumulation of CD57+CD28– T cells." (PMID 34122420, 2021). "Different subpopulations of T lymphocytes have different effects on atherosclerosis, Th1, Th17 cells, natural killer cells (NKT), CD28 null cells promote the process of atherosclerosis, while some of them are expressed on atherosclerotic plaques." (PMID 34833374, 2021). "Later CD28+ CD4+ CD25+ regulatory T cells were found to be a protective CD4 subset in atherosclerosis suggesting that CD28-null CD4 T cells are atherogenic." (PMID 31998318, 2019). "Protein phosphatase 5 (PP5) is a stress induced inhibitor of T cell ERK and JNK signaling in “senescent” CD4+CD28− T cells, also characterized by DNA demethylation and altered expression of genes that promote atherosclerosis." (PMID 28239687, 2016). "A recent study has shown that CD28 influence the atherosclerosis development by co-stimulating T-cell with CD80/86." (PMID 24079748, 2013). "Macrophages express CD80, CD86 and CD28 in human atherosclerosis lesions." (PMID 36703734, 2022). "Indeed, CD4+CD28− T cells were reported to be a major T cell subset observed among infiltrating cells at sites of inflammation and were found to be associated with atherosclerosis, suggesting that CD4+CD28− T cells take part in vascular plaque destabilization." (PMID 28596556, 2017). "The results indicate that PP5 increases expression of methylation sensitive T cell genes, and may contribute to the aberrant gene expression in CD4+CD28+ T cells that characterize lupus flares as well as the aberrant gene expression in CD4+CD28− T cells that promote atherosclerosis." (PMID 28239687, 2016). "To evaluate the proliferative capacity of T cells after MSC treatment, we isolated splenocytes eight weeks after induction of atherosclerosis by WTD feeding and cultured them in the presence of αCD3/CD28." (PMID 26490642, 2015). "It has been previously shown that co-stimulatory molecules of the B7/CD28 and tumor necrosis factor (TNF)/TNF receptor family are instrumental in T cell activation during atherosclerosis." (PMID 24691202, 2014). "The upregulated inflammatory pathways in CCCA include atherosclerosis and integrin signaling, lipid antigen presentation by CD1, CD28 signaling in T helper cells and NFkB and JAK/Stat signaling." (PMID 22685570, 2012). "Similarly, the expression levels of CD28, TRAT1, TRAV13-1, and LEF1 were related to smoking and smoking-related atherosclerosis." (PMID 37762221, 2023). "According to the previous studies, the data have shown that the CD28/CTLA-4-CD80/CD86 pathway plays an important role in accelerating the development of atherosclerotic lesions, and was considered as an important potential target in immune regulation of atherosclerosis." (PMID 35874761, 2022).
ovarian carcinoma (25 papers, 2011 to 2025). A malignant neoplasm originating from the surface ovarian epithelium. "In addition, actual count of CD39+ resting Treg AC was also shown to be causally associated with the development of ovarian cancer, whereas a high relative count of CD28+ CD45RA- CD8+ T cells reduced the risk of cervical cancer." (PMID 38434980, 2024). "High CD40 expression correlated with liver and bile duct, pancreatic, and ovarian cancers, as well as with CD28 and GITR transcripts." (PMID 41182434, 2025). "Whereas a study comparing chimeric receptors for NK cells with NKG2D ectodomain combined with CD3ζ, CD28-CD3ζ or 4-1BB-CD28-CD3ζ showed higher cytotoxicity against ovarian cancer with the construct containing only CD3ζ." (PMID 35919494, 2022). "In the present study, we compared effector functions and performed phenotypic analysis of MSLN-CAR T cells containing either a CD28 (M28z) or 4–1BB (MBBz) co-stimulatory domain in different in vitro models of ovarian cancer." (PMID 35898704, 2022). "There was also a trend towards lower level of CD8+CD28+ T cells in ovarian cancer patients compared to benign counterparts (malignant Vs." (PMID 35410290, 2022). "Our results showed that the decrease in post-operative CD8+CD28+ T cells and NK cells in both groups indicated that the post-operative antitumour immunity of ovarian cancer patients was suppressed." (PMID 34461965, 2021). "Two CD28-targeting BsAbs were developed, one for ovarian cancer (MUC16 × CD28) and another for prostate cancer (PSMA × CD28, REGN5678)." (PMID 34358141, 2021). "We therefore evaluated the contribution of CD28 in the expansion of TILs and PBLs collected from the same patient with ovarian cancer." (PMID 21827675, 2011). "Additionally, the superiority of CD28 costimulation was also observed in HER2-specific CAR-T-targeting ovarian carcinoma xenografts." (PMID 38516299, 2023). "CD3+CD8+ T and CD8+CD28+ T cells were significantly lower in ovarian cancer patients." (PMID 35410290, 2022). "In contrast, CD3+CD8+ T and CD8+CD28+ T cells were significantly lower in ovarian cancer patients." (PMID 35410290, 2022). "We deployed monospecific murine instead of polyclonal human T cells for CAR T cell generation to evaluate second generation L1CAM- and HER2-specific CARs with different spacer length and either the CD28 or 4-1BB co-stimulatory domain in mouse models of neuroblastoma and ovarian carcinoma." (PMID 33801448, 2021). "Similarly, a MUC16 × CD28 BsAb enhances the antitumor efficacy of CD3 BsAbs in a xenograft model of ovarian cancer." (PMID 34358141, 2021). "Furthermore, patients with ovarian cancer had a lower level of circulating CD8+CD28+ T cells." (PMID 36969245, 2023). "anti-αFR.CD3ζ, anti-αFR.CD28.CD3ζ and anti-αFR.CD28.4-1BB.CD3ζ, the latter presented the highest cytotoxicity, reflected in stronger degranulation and cytokine secretion, greater proliferation and longer persistence when incubated with αFR-expressing ovarian cancer cells." (PMID 34072732, 2021). "We tested antitumor activity of the derived CD28-OX-40- and 4-1BB-CAR-T/NK cells in Balb/c nude mice with xenografts of human ovarian cancer SKOV3." (PMID 37761005, 2023). "The median concentrations of the studied proteins (BTLA, CD27, CD28 and CD80) were statistically significantly higher in serum of patients in the ovarian cancer group (group A) compared to serum concentrations in patients with benign ovarian lesions (group B)." (PMID 35204342, 2022). "The cutoff values for BTLA, CD27, CD70, CD28 and CD80 that were elevated in the serum of patients with ovarian cancer were calculated using ROC curve analysis." (PMID 35204342, 2022). "Ovarian cancer patients have altered circulating lymphocyte profile (elevated Treg cell, depressed CD3+CD8+ T and CD8+CD28+ T cells)." (PMID 35410290, 2022).
ovarian carcinoma (continued). "When the induced in vitro differentiated T cells were activated by cytokines and anti-CD3/CD28 beads, CD8+ T cell receptor (TCR) γδ+ T cells were preferentially generated and elicited cytotoxic function against ovarian cancer cells in vitro." (PMID 34685611, 2021). "Not surprisingly, CD3+CD8+ T cells and CD8+CD28+ T cells were depressed in ovarian cancer patients compared to patients with benign tumor." (PMID 35410290, 2022). "BTLA, CD28 and CD80 may also contribute to the diagnosis of ovarian cancer, but their possible insufficient sensitivity and specificity as diagnostic markers should be taken into account." (PMID 35204342, 2022).